LGALS1 (galectin 1)
Diseases named in the same sentence as LGALS1 in open-access papers (continued):
Sharing a sentence is not in itself a finding about the gene and the disease.
myeloid malignancies (1 paper, 2024). "Collectively, the data presented here confirm a role for galectin-1 as a mediator of pathobiology in myeloid malignancies and worthy of further exploration as a therapeutic target that has the potential to modify the disease course." (PMID 39383242, 2024). "Ongoing work will be aimed at determining the mechanisms of action for galectin-1 in myeloid neoplasms, further validating the efficacy of galectin-1 targeting in additional disease models, and identifying the most clinically-tractable targeting modality." (PMID 39383242, 2024). "Previous studies have suggested modes of action for galectin-1 that may be relevant in myeloid malignancies." (PMID 39383242, 2024). "Given the disease modifying activity of the anti-galectin-1 antibody treatment in the MPLW515L mouse model, we hypothesized that high expression of galectin-1 may be detrimental more broadly in myeloid malignancies." (PMID 39383242, 2024). "Collectively, these results highlight galectin-1 as a central pathological mediator in myeloid malignancies, a promising biomarker, and a therapeutic target that may alter the disease course, which is not possible to achieve for the majority of patients using currently available medical therapies." (PMID 39383242, 2024). "A role for S100a6 and other S100 family members in inflammation and malignant hematopoiesis has previously been reported, whereas galectin-1 has not been extensively studied in myeloid malignancies." (PMID 39383242, 2024). "Targeting galectin-1 using small molecule glycan inhibitors, natural polysaccharides, peptides (OTX008) or anti-galectin-1 monoclonal antibodies may counteract fibrosis and also the immunomodulation that occurs in myeloid neoplasms." (PMID 39383242, 2024).
Myocardial fibrosis (1 paper, 2026). "The molecules TGF-β1, TNF-α, IL-6, galectin-3, and galectin-1 are critically involved in the cardiac inflammatory and profibrotic cascade, and they have been linked to myocardial fibrosis severity and to structural and electrical atrial remodeling." (PMID 41590667, 2026).
periapical granuloma (1 paper, 2024). Chronic nonsuppurative inflammation of periapical tissue resulting from irritation following pulp disease or endodontic treatment. "There is extensive research with inflammatory markers (e.g., Galectin 1 and 7, intercellular adhesion molecular-1, degranulated mast cells, TGFb, IFNd, TNFa, IL4, IL6), observing differences in expression between periapical cysts and periapical granulomas." (PMID 39691380, 2024).
peripheral T-cell lymphoma (1 paper, 2022). "The prognosis of peripheral T-cell lymphoma patients is significantly poor, and high intratumoral galectin-1 expression before treatment was associated with adverse outcomes in a cohort of patients with CD30+ and ALK− peripheral T-cell lymphoma." (PMID 35677161, 2022).
Peritoneal Fibrosis (1 paper, 2023). Disorder characterized by a wide range of structural changes in PERITONEUM, resulting from fibrogenic or inflammatory processes. "Galectin-1-induced peritoneal fibrosis may create a favorable environment for GC cell peritoneal metastasis." (PMID 37328752, 2023).
placental insufficiency (1 paper, 2020). Failure of the placenta to deliver an adequate supply of nutrients and oxygen to the fetus. "Therefore, the finding of downregulated LGALS1 expression in our FGR samples might be the key regulator leading to placental insufficiency-induced FGR, as well as an indication for the possible higher risk of developing long-term cardiovascular dysfunction in these offspring." (PMID 33256815, 2020). "Future studies should elucidate whether the downregulated LGALS1 and FPR3 expressions in FGR are angiogenesis-modulating regulators leading to placental insufficiency-induced FGR or whether the expression of these genes can be used as a biomarker for increased cardiovascular risk." (PMID 33256815, 2020).
Pneumocystis infection (1 paper, 2010). "Among the ten most down-regulated genes, the expression of the lectin, galactoside-binding, soluble, 1 (Lgals1) gene is most severely reduced by Pneumocystis infection." (PMID 20377877, 2010).
polycythemia (1 paper, 2024). Abnormally high mass or concentration of red blood cells in the blood, either due to an increase in erythropoiesis or a decrease in plasma volume. "Galectin-1 neutralization led to a reduction in bone marrow fibrosis and cellular architecture in the MPLW515L mice, and reduced the myeloproliferative phenotype with significantly reduced thrombocytosis, polycythemia and splenomegaly." (PMID 39383242, 2024).
prediabetes (1 paper, 2022). "Longitudinal studies on individuals converting from prediabetes to T2D should include repeated measurements of serum galectin-1." (PMID 36295832, 2022). "It would therefore be of interest to measure galectin-1 in prospective cohort studies to monitor the galectin-1 trajectory from normal to prediabetes and newly diagnosed T2D." (PMID 36295832, 2022).
retinal detachment (1 paper, 2018). An eye emergency condition which may lead to blindness if left untreated. "Neutralising galectin-1 activity in rat eyes is reported to increase susceptibility to retinal detachment due to weak RPE and neural retinal adhesion." (PMID 30176221, 2018).
scleroderma (1 paper, 2023). Scleroderma is a rare autoimmune connective tissue disorder characterized by abnormal hardening of the skin and, sometimes, other organs. "Genes associated with ECM components, such as COL4A1, heparan sulfate proteoglycan 2 (HSPG2), and actin beta (ACTB), as well as phospholipase C gamma 2 (PLCG2), fatty binding protein 4 (FABP4), and galectin 1 (LGALS1), also showed higher expression levels in scleroderma." (PMID 37443817, 2023). "PLCG2, FABP4, and LGALS1, which are involved in inflammatory pathways as well as pathways regarding leukocyte transendothelial migration, vascular smooth muscle contraction, and the pro-inflammatory PPAR signalling pathways that were upregulated were also upregulated in scleroderma ECs." (PMID 37443817, 2023).
spinal cord injury (1 paper, 2022). Penetrating and non-penetrating injuries to the spinal cord resulting from traumatic external forces (e.g., WOUNDS, GUNSHOT; WHIPLASH INJURIES; etc.). "Another study showed that galectin-1 interacts with the Neuropilin-1/PlexinA4 receptor complex in damaged neurons to contribute to axonal regeneration and locomotor recovery after spinal cord injury." (PMID 36008956, 2022).
steatosis (1 paper, 2022). Increased lipid within the cytoplasm of cells. "Coincident with an alleviation of hepatic steatosis, we computationally detected the downregulation of IL-6/JAK/STAT3 signaling and the inflammatory response (e.g., Tlr8, Mlkl), together with impaired EMT (Lgals1) in the liver, while the expression of genes related to mTOR was enhanced by LY." (PMID 35737463, 2022).
Telangiectasia (1 paper, 2023). Telangiectasias refer to small dilated blood vessels located near the surface of the skin or mucous membranes, measuring between 0.5 and 1 millimeter in diameter. "In SSc, higher concentrations of galectin 1 were associated with the presence of telangiectasias, while lower galectin 1 levels were present in patients with pitting scars/DUs, suggesting that this molecule may be a protective factor against the development of SSc-related digital vasculopathy." (PMID 36835506, 2023).
Thrombocytopenia (1 paper, 2024). A reduction in the number of circulating thrombocytes. "Our findings indicated that P-selectin is the most effective molecule conjugated to the liposome, facilitating rescue from TAA-induced increases in circulating ALT and thrombocytopenia, compared to other proteins such as E-selectin, L-selectin, galectin-1, CLEC2, and anti-PSGL-1 Ig." (PMID 39513885, 2024).
Thromboembolism (1 paper, 2021). The formation of a blood clot inside a blood vessel that subsequently travels through the blood stream from the site where it formed to another location in the body, generally leading to vascular occlusion at the distant site. "Although there are no results regarding LGALS1 and VTE, this potential biomarker crosstalk gene could be a hint for a bacterial interlink, i.e., the epithelial invasion of periodontal pathogens resulting in inflammation and thromboembolism as a systemic effect." (PMID 34925639, 2021).
thrombosis (1 paper, 2023). "Patients with MPV thrombosis had higher serum CLEC-2 (1012.55 ± 674.39 pg/mL vs. 753.14 ± 507.06 pg/mL, p = 0.020) and galectin-1 (96.67 ± 79.43 pg/mL vs. 61.95 ± 56.32 pg/mL, p = 0.066) levels than those without PVST." (PMID 37720512, 2023). "Some animal studies have demonstrated a relationship of CLEC-2 and galectin-1 with venous thrombosis, but human studies are lacking." (PMID 37720512, 2023). "Indeed, the mean age was significantly higher in our patients with MPV thrombosis than those without PVST, suggesting that age might weaken the difference in serum galectin-1 level between the two groups." (PMID 37720512, 2023).
thyroid (1 paper, 2025). "According to these results, a combination of immunohistochemical markers like galectin 1 and TROP-2 can be recommended as initial panels to help accurately diagnose thyroid follicular lesions with challenging morphological features." (PMID 41480246, 2025).
undifferentiated carcinoma (1 paper, 2014). A usually aggressive malignant epithelial neoplasm composed of atypical cells which do not display evidence of glandular, squamous, or transitional cell differentiation. "Similarly, galectin-1 was found to be increased in endometrioid EMCAR from well differentiated to undifferentiated carcinoma." (PMID 24658839, 2014).
uterine tumors (1 paper, 2014). "In the current research, we have evaluated the expression of PD-L1, PD-L2, B7-H4, IDO, galectin-1 and galectin-3 in uterine tumors and documented the arginase-1 activity and MDSC infiltration in these tumors." (PMID 24658839, 2014). "In addition, we have analyzed the expression of galectin-1 and 3 in uterine tissue samples by ELISA and confirmed galectin-3 expression on cellular subtypes in uterine tumor specimens by flow cytometry." (PMID 24658839, 2014). "In conclusion, we report the presence of the immune checkpoints PD-L1/PD-L2 and B7-H4 in uterine tumors as well as the presence of the immune inhibitory molecules IDO, arginase-1, galectin-1 and galectin-3 and the immunosuppressive MDSC." (PMID 24658839, 2014). "In an attempt to shed more light on the immunosuppressive environment in uterine tumors, we analyzed the presence of PD-L1, PD-L2, B7-H4, indoleamine 2,3-dioxygenase (IDO), galectin-1, galectin-3, arginase-1 activity and myeloid-derived suppressor cell (MDSC) infiltration." (PMID 24658839, 2014).
ZIKV infection (1 paper, 2022). "Silencing or overexpressing LGALS1 is less efficient in HNPCs, making the system difficult to assess the function of LGALS1 in ZIKV infection." (PMID 36404916, 2022). "Most importantly, Lgals1−/− mice are much more resistant to ZIKV infection compared to Lgals1+/+ littermates." (PMID 36404916, 2022). "In contrast, functional analysis of ZIKV infection in A549 and mouse neural cells (MNCs) is easier, and these cells also express galectin-1 on the cell surface." (PMID 36404916, 2022). "Collectively, these results provide strong evidence that galectin-1 plays a critical role in ZIKV infection and pathogenesis." (PMID 36404916, 2022). "The results showed that Lgals1 null mice were significantly more resistant to ZIKV infection compared to their wild-type (WT) littermates." (PMID 36404916, 2022). "The strongest evidence supporting that galectin-1 is important in ZIKV infection came from experiments showing that Lgals1−/− mice were significantly more resistant to ZIKV infection compared to their WT littermates." (PMID 36404916, 2022). "Although all our in vitro and in vivo experiments support the notion that galectin-1 plays a pivotal role in ZIKV infection, we cannot exclude the possibility that additional receptors are also involved in ZIKV infection." (PMID 36404916, 2022). "Importantly, Lgals1−/− mice are significantly more resistant to ZIKV infection than Lgals1+/+ littermates are, having significantly lower virus titers and fewer pathologies in various organs." (PMID 36404916, 2022). "Accordingly, at 72 h after ZIKV infection (MOI = 0.01), the ZIKV E protein levels were also greatly decreased in galectin-1 silenced MNCs by 62 to 83%." (PMID 36404916, 2022). "Most importantly, we also identify a novel ZIKV entry factor galectin-1, whose importance in ZIKV infection has not been reported before." (PMID 36404916, 2022).
tumor (380 papers, 2005 to 2026). "The galectin-1-targeting peptide (P7) selectively binds to galectin-1-expressing tumors, a protein linked to immune evasion and tumor progression." (PMID 40286158, 2025). "CA125 interacts with specific ligands, including galectin-1/3, mesothelin, and Siglec-9, which play key roles in regulating tumorigenesis, progression, migration, invasion, and tumor immunity through various signaling pathways associated with cancer." (PMID 40458729, 2025). "Apart from the prominent role in VEGF/VEGFR signaling, ample studies have linked galectin-1 to tumor progression by increasing endothelial cell proliferation and migration, thus facilitating endothelial cell sprouting, tube formation and tumor vascularization." (PMID 38990363, 2024). "NK cells eliminate tumor cells by releasing cytotoxic granules containing granzyme B, and among the immunosuppressive mechanisms associated to NK cells, secreted galectin-1 hinders the tumor-killing effects of these cells by reducing the release of granzyme B." (PMID 38160212, 2024). "A key role of galectin-1 in tumor angiogenesis is linked to activation of pro-angiogenic signaling by the vascular endothelial growth factor (VEGF)." (PMID 38990363, 2024). "GC CAFs highly express galectin-1 (Gal-1, encoded by the LGALS1 gene), which regulates tumor cell malignant biological behaviors." (PMID 37328752, 2023). "Like PD-L1, tumor cells and tumor-associated ECs overexpress a protein called galectin 1, which induces apoptosis and exhaustion in resting T cells, limiting their infiltration and function." (PMID 37727791, 2023). "As a critical regulator of tumor immune evasion, high LGALS1 expression in AML patients is associated with higher macrophage M2 monocyte infiltration." (PMID 38273850, 2023). "For instance, galectin-1 downregulation in transformed and tumor-associated stroma cells have demonstrated beneficial effects in pre-clinical studies." (PMID 36703969, 2022). "In that regard, in other tumor types, like colorectal cancer and glioma, it has been found that galectin-1 serum levels can have diagnostic and predictive value." (PMID 36497271, 2022). "Proteomics confirmed that galectin-1 expression in the tumor microenvironment is associated with poor clinical outcomes of cHL." (PMID 35677161, 2022). "Growing evidence indicates that overexpression of LGALS1 is associated with metastasis formation, tumour recurrence and poor tumour prognosis." (PMID 35632759, 2022). "Galectin-1-deficient mice had reduced tumor growth, increased NK cell infiltration, and elevated granzyme B expression proving an inhibitory effect of galectin-1 on NK cell antitumor function." (PMID 34209508, 2021). "MDSCs cause γδ T cells to secrete galectin-1, thus attenuating anti-tumor immunity in sarcoma mice models." (PMID 33708214, 2021). "As with galectin-1, the expression levels of galectin-3 are higher in the more invasive sections of the tumor and the cells associated with peripheral vessels." (PMID 35008740, 2021). "Gal-1 is a glycoprotein encoded by the LGALS1 gene and known to exert immunomodulatory effects including mediating tumor-immune escape." (PMID 34568045, 2021). "Galectin-1 (Gal-1) is a secretory lectin with pro-tumor activities and is associated strongly with hepatocellular carcinoma (HCC) development." (PMID 34552935, 2021). "Recent reviews and meta-analyses have demonstrated that galectin-1 is associated with tumor formation, progression, metastasis, angiogenesis, and prognosis in several kinds of cancer." (PMID 31996694, 2020). "Our previous findings suggest that the galectin-1-increased expression in UBUC is intimately associated with the primary tumor status, grade, and invasion." (PMID 29671787, 2018). "It is found that tumor stages, tumor invasiveness, and metastasis are associated with the increased galectin-1 expression in UBUC." (PMID 29671787, 2018).